CCNA1 (cyclin A1)
Description:
May be involved in the control of the cell cycle at the G1/S (start) and G2/M (mitosis) transitions. May primarily function in the control of the germline meiotic cell cycle and additionally in the control of mitotic cell cycle in some somatic cells.
Synonyms: CT146
Tractability: Small molecule: a high-quality ligand is known; it belongs to a druggable protein family. PROTAC: UniProt records ubiquitination sites on it; a small molecule that binds it is known.
Gene: Protein-coding gene on chromosome 13 (36,431,520 to 36,442,870, forward strand). Ensembl gene ENSG00000133101.
Subcellular location: Nucleus
Subcellular location (Human Protein Atlas): Nuclear bodies; Nucleoplasm
Pathways (Reactome):
Cell Cycle: Cdc20:Phospho-APC/C mediated degradation of Cyclin A; Chk1/Chk2(Cds1) mediated inactivation of Cyclin B:Cdk1 complex; Cyclin A/B1/B2 associated events during G2/M transition; Cyclin A:Cdk2-associated events at S phase entry; G0 and Early G1; G1/S-Specific Transcription; G2 Phase; G2/M DNA replication checkpoint; Regulation of APC/C activators between G1/S and early anaphase; SCF(Skp2)-mediated degradation of p27/p21; Telomere Extension By Telomerase
Cellular responses to stimuli: DNA Damage/Telomere Stress Induced Senescence; Senescence-Associated Secretory Phenotype (SASP)
DNA Replication: CDK-mediated phosphorylation and removal of Cdc6; Orc1 removal from chromatin
DNA Repair: Processing of DNA double-strand break ends
Metabolism of proteins: Ub-specific processing proteases
Gene Ontology:
Molecular function: protein binding; cyclin-dependent protein serine/threonine kinase regulator activity
Biological process: male meiosis I; spermatogenesis
Cellular component: microtubule cytoskeleton; cyclin A1-CDK1 complex; cyclin A1-CDK2 complex; cyclin A2-CDK2 complex; cytosol; microtubule organizing center; nucleoplasm; nucleus
Genetic constraint (gnomAD): Loss-of-function variants: 19 observed, 47.79 expected, observed/expected ratio (o/e) 0.4, 90% interval 0.28 to 0.58. The upper end of that interval is the gene's LOEUF score, 0.58, which puts it in group 2 of 6, group 1 being the genes least tolerant of losing a copy. Missense variants: 412 observed, 526.3 expected, observed/expected ratio (o/e) 0.78, 90% interval 0.72 to 0.85. Synonymous variants: 193 observed, 205.3 expected, observed/expected ratio (o/e) 0.94, 90% interval 0.83 to 1.06.
Homologues: Orthologues: chimpanzee CCNA1 (100% identical), macaque CCNA1 (97% identical), dog CCNA1 (89% identical), pig CCNA1 (88% identical), rabbit CCNA1 (87% identical), guinea pig CCNA1 (85% identical), rat Ccna1 (85% identical), mouse Ccna1 (84% identical), tropical clawed frog ccna1 (60% identical), zebrafish ccna1 (51% identical), Drosophila melanogaster CycB (24% identical), Caenorhabditis elegans cyb-1 (24% identical), and 6 more. Paralogues in human: CCNA2 (48% identical), CCNB2 (27% identical), CCNB1 (27% identical), CCNB3 (27% identical), CCNF (21% identical), CCNE2 (20% identical), CCNE1 (19% identical), CCND3 (19% identical), CCNO (19% identical), CCND2 (18% identical), CCNJ (17% identical), CCND1 (17% identical), and 6 more.
Diseases named in the same sentence as CCNA1 in open-access papers:
CCNA1 is named in the same sentence as 76 diseases in open-access papers, as found by Europe PMC text mining. Sharing a sentence is not in itself a finding about the gene and the disease. The quoted sentences say what the papers report.
breast carcinoma (26 papers, 2006 to 2026). "In breast cancer cells, the deletion of KDM4B not only reduces the transcription of WEE1, CCND1, and CCNA1, but also disrupts the estrogen-induced cell cycle G1-S phase transition, causing breast cancer cells to stall at the G2-M phase or G1-S phase." (PMID 35186950, 2021). "Our findings suggest that cyclin A1 associated pathways play important roles in breast cancer progression." (PMID 23991063, 2013). "Evidence in the literature showed that the differential methylation pattern of CCNA1 was associated with the treatment response in breast cancer and could potentially be a predictive marker to anthracycline/mitomycine sensitivity." (PMID 36418365, 2022). "SMYD3 suppresses the methylation of H2A.Z1, thereby inhibiting Anp32e-mediated dissociation of H2A.Z1 from chromatin, increasing cyclin A1 expression, and encouraging breast cancer progression." (PMID 39199381, 2024). "KDM8 promotes breast cancer cell proliferation by activating CCNA1, a regulator of the G1/S and G2/M transition." (PMID 37893043, 2023). "It has been reported that cyclin A1 and cyclin D1 were transcriptional targets of SIX1 and that SIX1 promoted cell proliferation in breast cancer by increasing cyclin A1 expression and in pancreatic cancer via increasing cyclin D1 expression." (PMID 35287543, 2022). "Of note, it has been reported that the downregulation of CCNA1 leads to cell growth in the context of breast cancer." (PMID 34047951, 2021). "SMYD3 mediated-H2A.Z methylation has also been shown to trigger cyclin A1 gene expression, leading to cell cycle activation in breast cancer cells." (PMID 33333978, 2020). "It has been reported that SIX1 showed great influence on cell proliferation, survival, and motility by transcriptional regulating cyclin D1 and c-myc in rhabdomyosarcoma and cyclin A1 in breast cancer in vitro." (PMID 27821176, 2016). "On the other hand, cell cycle regulatory pathways play an important role in estrogen related breast cancer cell growth, in which Cyclin A1 plays important role in tumor development." (PMID 27110560, 2016). "In breast cancer, the H3K36me2 demethylase activity is essential for CCNA1 transcription and cell proliferation, by contrast, in HCC, our data revealed that the enzyme activity is seemingly unnecessary for CDKN1A activation and cell proliferation." (PMID 26760772, 2016). "Elevated levels of Cyclin A1 are needed to promote tumorigenic behavior in various solid tumors, including breast cancer." (PMID 25068292, 2014). "Our findings suggest that cyclin A1 is involved in breast cancer progression in addition to its role in the initiation of leukemia and prostate cancer." (PMID 23991063, 2013). "Our data showed that induction of cyclin A1 overexpression in breast cancer cell line MCF-7 promoted cancer cell invasion and increased the expression of VEGF and ER-α." (PMID 23991063, 2013). "High level of cyclin A1 mRNA expression has also been observed in various types of breast cancer cell lines." (PMID 23991063, 2013). "MDA-MB-231 cells that represented most aggressive type of breast cancer cells showed highest level of cyclin A1 protein expression, while MCF-7 cells that represented non-invasive and ER-α positive breast cancer displayed relatively low cyclin A1 expression." (PMID 23991063, 2013). "It actively promotes tumorigenesis of breast cancer by reactivation of Cyclin A1, and c-myc is transcriptionally regulated by Six1 in rhabdomyosarcoma tumor cells." (PMID 23527134, 2013). "Cyclin A1 expression also correlated with a proliferation marker Ki67 in breast cancer specimens from the 94-patient cohort (r2=0.255 p<0.05)." (PMID 23991063, 2013). "Virtually all breast cancer metastatic lesions examined showed high level of cyclin A1 and VEGF expression." (PMID 23991063, 2013). "Induction of cyclin A1 overexpression in breast cancer cell line MCF-7 results in an enhanced invasiveness and a concomitant increase in VEGF expression." (PMID 23991063, 2013).
breast carcinoma (continued). "Cyclin A1 therefore plays an important role in breast cancer progression by influencing both VEGF and ER-α pathways." (PMID 23991063, 2013). "In the present study, we investigate a role of cyclin A1 in breast cancer progression by employing breast cancer cell lines and xenograft mouse models." (PMID 23991063, 2013). "Immunohistochemical analysis showed that level of cyclin A1 expression was elevated in the majority breast cancer specimens (89%) in a 94-patient cohort and 79% in a 48-patient cohort, as shown in the representative images." (PMID 23991063, 2013). "We further show that cyclin A1 is highly expressed in primary breast cancer specimens and metastatic lesions from breast cancer patients." (PMID 23991063, 2013). "Cyclin A1 is a downstream effector for Six1 in breast cancer where overexpression of Six1 promotes cyclin A1 expression and subsequently increases cell proliferation and progression." (PMID 17008870, 2006). "Activates the expression of cyclin A1, thus promoting breast cancer development." (PMID 39199381, 2024). "In addition to its association with tumorigenesis, SMYD3 has also been reported to methylate histone H2A.Z.1 at lysine 101 in the promoter of cyclin A1, promoting cyclin A1 transcription in breast cancer." (PMID 38191478, 2024). "The reduced proliferation potential of the cells does not seem to interfere with their migratory potential, as it has also been observed, for example, that the downregulation of cyclin A1 in a breast cancer cell line increases migration and decreases proliferation." (PMID 37572121, 2023). "Hence, our finding indicates that the expression of Cyclin A1 in tumor sample correlates with the involvement of various cell signaling pathways like cell cycle regulators and estrogen receptor signaling in breast cancer progression." (PMID 27110560, 2016). "VEGF expression was similar to what was observed for cyclin A1 in breast cancer specimens." (PMID 23991063, 2013). "To investigate whether cyclin A1 may be involved in breast cancer progression and may be linked to VEGF pathways, we examined cyclin A1 and VEGF expression in various types of breast cancer cell lines (n=6)." (PMID 23991063, 2013). "In the present study, we tested our hypothesis on that cyclin A1 overexpression may promote growth and invasion of breast cancer cells." (PMID 23991063, 2013). "To obtain information on cyclin A1 expression in breast cancer specimens, we examined cyclin A1 expression in two sets of TMAs that contained tissues from clinically and pathologically annotated breast cancer cases." (PMID 23991063, 2013). "To investigate whether expression of cyclin A1 and VEGF may be linked to breast cancer progression, we examined cyclin A1 and VEGF expression in breast cancer metastatic lesions." (PMID 23991063, 2013). "It will be of interesting to investigate whether MMPs may be involved in mediating invasion of ER-α positive breast cancers in cooperation with cyclin A1, ER-α and VEGF." (PMID 23991063, 2013). "We therefore assessed whether cyclin A1 expression may correlate with VEGF expression in the two breast cancer cohorts." (PMID 23991063, 2013). "To elucidate biological consequences of cyclin A1 overexpression in breast cancer cells, we established mouse tumor xenograft models in which we implanted subcutaneously MCF-7 cells transfected with cyclin A1-pCMS-EGFP or pCMS-EGFP vectors into female nude mice." (PMID 23991063, 2013). "Next, we asked whether VEGF may be involved in mediating the invasive behaviour of breast cancer cells that overexpress cyclin A1." (PMID 23991063, 2013). "Six1 elevated in breast cancer promotes tumour progression through direct activation of Cyclin A1." (PMID 17008870, 2006).
breast carcinoma (continued). "Elevated expression of the CCNA1 gene and protein has been reported in various tumor conditions, such as PTC when associated with pituitary homeobox 2 (PITX2) transcriptional factor, breast cancer when associated with Six1 homeoprotein, prostate cancer, leukemic myeloid and ovarian cancer." (PMID 40722651, 2025). "Thus our study suggests a clinical importance of cyclin A1 expression in breast cancer." (PMID 23991063, 2013). "Given the important role of cyclin A1 and its functional link with ER-α and VEGF which have been identified in the present study, it is of interesting to investigate whether cyclin A1 may play an important in modulating treatment response of breast cancer in laboratory and clinical settings." (PMID 23991063, 2013). "Based on our observations in primary breast cancer specimens and metastatic lesions, and our data from functional analysis in breast cancer cell lines, we hypothesized that altered cyclin A1 expression may contribute to breast cancer progression in cooperation with VEGF and ER-α." (PMID 23991063, 2013). "In breast cancer (BC) cells, SMYD3 can regulate the cell cycle and promote cancer cell migration by combining with the cyclin A1 (CCNA1) and myosin light chain 9 (MYL9) promoters." (PMID 34335697, 2021). "As CDK1 is a major kinase partner to cyclin A1, our data show that altered expression of cyclin A1 also leads to an alteration in CDK1 expression in breast cancer cells." (PMID 23991063, 2013). "There is a statistically significant correlation between cyclin A1 and VEGF expression in breast cancer specimens from two patient cohorts (p<0.01)." (PMID 23991063, 2013). "Correlation coefficients between levels of expression of cyclin A1, VEGF and Ki67 in breast cancer specimens." (PMID 23991063, 2013). "As tamoxifen inhibits E2 effect in ER-α positive breast cancer cells by interfering ER-α, we then examined the effect of E2 and tamoxifin combination treatment on MCF-7 cells transfected with cyclin A1-pCMS-EGFP or pCMS-EGFP." (PMID 23991063, 2013). "Induction of cyclin A1 expression leads to an increase in ER-α expression in MCF-7 and T47D cells which are estrogen responsive breast cancer cells." (PMID 23991063, 2013). "To further understand the mechanisms by which cyclin A1 promotes the invasiveness of breast cancer cells, we investigate whether cyclin A1 is functionally linked to VEGF by using breast cancer cell lines that are either positive or negative for ER-α expression." (PMID 23991063, 2013). "Furthermore, in breast cancer, SMYD3 drives cell cycle progression by upregulating the transcription of cyclin A1 whereas, in hepatocellular carcinoma, SMYD3 promotes proliferation through stimulating CDK2 transcription." (PMID 35406445, 2022). "To investigate whether induced cyclin A1 overexpression may lead to alterations in ER-α expression in breast cancer cells, we examined ER-α expression in MCF-7, MDA-MB231 and T47D cells which were transfected with cyclin A1-pCMS-EGFP or pCMS-EGFP vectors." (PMID 23991063, 2013). "Besides breast cancer cells, blockage of c-Myc and TGF-β pathways in Smyca-overexpressing HCC cell line NTU-BL also showed contrasting effects on cell proliferation and the expression of cell cycle regulators CDKN1A and CCNA1 (also known as cyclin A1)." (PMID 35794621, 2022). "Our finding on that cyclin A1 is involved in the modulation of both ER-α and VEGF pathways may provide novel insights into treatment of breast cancer and may be helpful for designing novel drugs to selectively target invasive breast cancer cells in clinical settings." (PMID 23991063, 2013). "To investigate whether cyclin A1 together with VEGF may play an important role in breast cancer progression and invasion, we performed functional analysis by employing three different breast cancer lines: MCF-7, MDA-MB-231 and T47D." (PMID 23991063, 2013).
breast carcinoma (continued). "MCF-7 cells are the non-metastatic breast cancer cells and express ER-α while MDA-MB-231 cells have metastatic potentials and lack the expression of ER-α, and T47D is ER-α positive cell line but express low level of endogenous VEGF and cyclin A1." (PMID 23991063, 2013).
cervical cancer (24 papers, 2006 to 2024). A primary or metastatic malignant neoplasm involving the cervix. "The aim of this study was to evaluate epigenetic status of cyclin A1 in human papillomavirus-associated cervical cancer." (PMID 16524460, 2006). "In cervical cancer Cyclin A1 methylation could be associated with decreased protein expression and the integrated form of HPV." (PMID 22712549, 2012). "The abnormal methylation of the promoter of the CCNA1 gene is closely related to the occurrence, growth, invasion, and metastasis of malignant tumors, such as cervical cancer." (PMID 36092717, 2022). "Hypermethylation has been observed in the pre-cursor lesions of cervical cancer, with the increasing methylation of CCNA1 from low grade to high grade cervical lesions being suggested as a diagnostic marker for progression." (PMID 34696474, 2021). "All of these results demonstrated that HK2 promoted cell proliferation and tumor formation in human cervical cancer cells by up-regulating cyclin A1, c-myc, and down-regulating p27 expression through the activation of ERK." (PMID 33324557, 2020). "For human cervical cancer, it has been reported that HPV infection is associated with promoter methylation of cyclin A1 (CCNA1) gene, thereby affecting its expression." (PMID 33050217, 2020). "Methylated HS3ST2, CCNA1, EGFR promoter, FHIT, TFPI2, CpG6, and CpG15 sites were associated with HPV16 infection in the progression of cervical cancer." (PMID 29850477, 2018). "On the other hand, it has also been reported that up-regulation of CCNA1 in cervical cancer is due to demethylation of the CpG island in its promoter." (PMID 23112860, 2012). "If the enhanced methylation frequency of Cyclin A1 found in HNSCC and Cervical Cancer is directly caused by the HP-virus and the overexpression of Cyclin A1 is only an indirect consequence of the altered cell cycle needs to be proven in further experiments." (PMID 22712549, 2012). "CCNA1 (at position 49) was included as a positive control for the highest listed, reported cervical cancer specific methylation gene promoter." (PMID 19025626, 2008). "We observed the same methylation profile for CCNA1 that was reported previously as a cervical cancer specific gene with hypermethylation in only 6 of 10 tumours but none of the 5 normals." (PMID 19025626, 2008). "We demonstrated cyclin A1 methylation to be commonly found in cervical cancer, both in vitro and in vivo, with its physiological role being to decrease gene expression." (PMID 16524460, 2006). "This methylation study indicated that cyclin A1 is a potential tumor marker for early diagnosis of invasive cervical cancer." (PMID 16524460, 2006). "More important, this study demonstrated that not only is cyclin A1 promoter hypermethylation strikingly common in cervical cancer, but is also specific to the invasive phenotype in comparison with other histopathological stages during multistep carcinogenesis." (PMID 16524460, 2006). "Epigenetic inactivation of CCNA1 is responsible for advancement of cervical cancer, but silencing of this gene might be responsible for progression of pituitary prolactinoma." (PMID 33709028, 2021). "For this, the cervical cancer line HeLa was transfected with HLA-A*02:01 and Cyclin A1." (PMID 32157447, 2020). "Therefore, our data demonstrated that HK2 promoted the proliferation of cervical cancer cells by upregulating cyclin A1 and down-regulating p27 expression through the Raf/MEK/ERK signaling pathway." (PMID 33324557, 2020). "In conclusion, this study demonstrated that HK2 could activate ERK1/2 through the Raf/MEK signaling pathway, further promoting cell proliferation and tumor formation by inducing cyclin A1, c-myc and reducing p27 in cervical cancer cells." (PMID 33324557, 2020). "CCNA1 may be an important tumor suppressor gene that plays a crucial part in head and neck carcinoma and cervical cancers." (PMID 33112548, 2020).